SEMA3F (semaphorin 3F)
Diseases named in the same sentence as SEMA3F in open-access papers (continued):
Sharing a sentence is not in itself a finding about the gene and the disease.
colorectal cancer (6 papers, 2014 to 2025). A primary or metastatic malignant neoplasm that affects the colon or rectum. "Interestingly, Sema3F expression is also associated with reduced progression of lung and colorectal cancers, suggesting it has unique contributions to cellular genomic stability." (PMID 29854302, 2018). "The role of SEMA3F in angiogenesis was shown in mouse model of colorectal cancer stably expressing recombinant SEMA3F." (PMID 34209679, 2021). "Although SEMA3F inhibits growth, metastasis and invasion of breast, lung and colorectal cancers, it also promotes metastasis and invasion of hepatocellular carcinoma through unknown targets that distinctly activate the focal adhesion pathway." (PMID 41391772, 2025). "Inactivation of Semaphorin 3F (SEMA3F) is involved in colorectal cancer development." (PMID 33109776, 2020). "Furthermore, higher expression of SEMA3F is correlated with better outcomes for various types of cancer patients, including osteosarcoma, esophageal cancer, breast cancer, head and neck squamous carcinoma, colorectal cancer, and prostate cancer." (PMID 41391772, 2025).
ovarian carcinoma (5 papers, 2009 to 2020). A malignant neoplasm originating from the surface ovarian epithelium. "SEMA3F has been reported to function as a tumour suppressor inhibiting tumour growth and invasion in a number of cancer types, including lung, prostate, bladder, osteosarcoma, ovarian cancer, and melanoma cancer." (PMID 32241267, 2020). "Interestingly, a significantly reduced expression of Sema3B (83 kDa), Sema3F (90 kDa), and plexin-A3 was observed in human ovarian cancer cell lines when compared with normal human ovarian surface epithelial cells." (PMID 24065959, 2013).
Anxiety (4 papers, 2015 to 2022). Intense feelings of nervousness, tension, or panic often arise in response to interpersonal stresses. "Thus, our findings suggest that Sema3F plays important roles in the development of neuronal circuitry underlying the regulation of some aspects of anxiety and fear responses." (PMID 26856818, 2016). "SEMA3F, the class 3 subfamily of semaphorins, was found to contribute to the development of neuronal circuitry related to anxiety and fear responses in SEMA3F-knockout mice." (PMID 35391799, 2022). "We demonstrated that Sema3F KO mice show increased anxiety- and fear-related behaviors and enhanced fear memory, suggesting an important role of Sema3F in regulating innate and learned fear responses and memory functions." (PMID 26856818, 2016). "Sema3F KO and WT control mice were compared in behavioral tests for assessing anxiety-related behavior, including light/dark transition, open field, elevated plus maze, and social interaction tests." (PMID 26856818, 2016). "Together, these results from the different types of tests for assessing anxiety-related behavior indicate that Sema3F KO mice exhibit decreased locomotor activity and abnormal anxiety-related behaviors in novel environments." (PMID 26856818, 2016). "In addition, in the social interaction test, which has also been used to assess anxiety, Sema3F knock-out mice show reduced duration of active social contact with a stranger mouse compared with controls." (PMID 34045951, 2021). "In addition, in the social interaction test, which has also been used to assess anxiety, Sema3F KO mice showed decreased distance traveled and reduced duration of active social contact with a novel environment with a stranger mouse compared with WT controls." (PMID 26856818, 2016). "Furthermore, our data show that these defects in the spinal motor circuitry do not affect general locomotion and anxiety related behavior in Sema3F knockout mice, as identified by the Open Field and CatWalk test." (PMID 25874621, 2015).
autism (4 papers, 2019 to 2024). Persistent deficits in social interaction and communication and interaction as well as a markedly restricted repertoire of activity and interest as well as repetitive patterns of behavior. "Along with GWAS on autism, a few recent studies suggested the association of Sema5A and Sema3F with ASD." (PMID 32443632, 2020). "Thus, PlxnA2−/− mice exhibit symptoms of Schizophrenia, Sema3F−/− mice exhibit symptoms of anxiety and autism, and Sema5A−/− mice exhibit symptoms of autism." (PMID 38646100, 2024).
head and neck squamous cell carcinoma (4 papers, 2015 to 2024). A squamous cell carcinoma that arises from any of the following anatomic sites: lip and oral cavity, nasal cavity, paranasal sinuses, pharynx, larynx, and salivary glands. "Additionally, in a model of head and neck squamous cell carcinoma, genomic loss of Sema3F correlated with increased metastasis and decreased survival, suggesting that Sema3F promotes LEC collapse and inhibits lymphangiogenesis in vivo." (PMID 36672254, 2023). "Similarly, recombinant semaphorin 3F also promotes LEC collapse and potently inhibits lymphangiogenesis in vivo and may represent an antilymphangiogenic metastasis suppressor gene in head and neck squamous cell carcinomas (HNSCC)." (PMID 28036019, 2016).
hepatocellular carcinoma (4 papers, 2021 to 2024). A malignant tumor that arises from hepatocytes. "Among these miRNAs, let-7c-5p was obviously downregulated and negatively related to SEMA3F in hepatocellular carcinoma and its upregulation was positively correlated with GC prognosis." (PMID 37926757, 2023). "A number of studies reported that SEMA3F, UCK2, NOL10, RAP2A, ZIC2 and SAC3D1 are associated with prognosis and tumour immune infiltration in hepatocellular carcinomas." (PMID 34760691, 2021). "Transcriptome profiling of hepatocellular carcinomas suggests that SEMA3F may promote metastasis development by activating focal adhesion pathways." (PMID 39232098, 2024). "In hepatocellular carcinoma (HCC), a high SEMA3F expression could be correlated with an unfavorable survival." (PMID 39232098, 2024).
breast tumor (3 papers, 2015 to 2017). "This is consistent with the finding showing SEMA3F, a direct RORα target gene with a ROR element, suppresses breast tumor invasion." (PMID 28052040, 2017). "Five genes (SEMA3F, BLVRB, PTPRF, MARCKS, and CQQ6) are up regulated both in HER2 positive cell lines and in high HER2 expressing primary breast tumor tissues." (PMID 25428913, 2015).
colon cancer (3 papers, 2016 to 2022). "Recently, it has been reported that retinoic acid receptor-related orphan receptor α (ROR α), Achaete scute-like 2 (ASCL2) and DNA inhibitor binding/differentiation 2 (Id2) bind the promoter region of SEMA3F in colon cancer." (PMID 36119535, 2022). "Transfection of colon cancer cells with Sema3F, another member of the Sema3 family, reduces integrin-αvβ3 expression and inhibits adhesion to fibronectin." (PMID 26755661, 2016).
esophageal squamous cell carcinoma (3 papers, 2022 to 2024). Esophageal squamous cell carcinoma (ESCC) is a type of esophageal carcinoma (EC) that can affect any part of the esophagus, but is usually located in the upper or middle third. "Conversely, SEMA3F is characterized as a tumor suppressor gene in esophageal squamous cell carcinoma, where low mRNA expression levels of SEMA3F are associated with poor survival outcomes and a positive lymph node status." (PMID 39232098, 2024). "The expression of semaphorin 3F (SEMA3F), a Nrp2 ligand that negatively regulates VEGFR3 activation, is downregulated in esophageal squamous cell carcinoma and is associated with increased VEGF-C and Nrp2 expression." (PMID 38201272, 2023).
lymph node metastases (3 papers, 2012 to 2024). "In line with our data, high SEMA3F expression is correlated with a lower risk of occult lymph node metastases in HNSCC25." (PMID 39232098, 2024). "In our patient cohort, high SEMA3F expression was correlated with a less frequent occurrence of lymph node metastases in esophageal adenocarcinoma (p = 0.041)." (PMID 39232098, 2024). "Comparing the results obtained with the patients of the TCGA with our sample, we can observe that predictive capacity of the transcriptional expression of the SEMA3F/NRP2 genes in detecting the presence of occult lymph node metastases was maintained." (PMID 35565388, 2022). "Consequently, the objective of this study was to assess NRP2 and its ligand SEMA3F as potential biomarkers for patient survival and their ability to predict lymph node metastases in esophageal adenocarcinoma." (PMID 39232098, 2024). "Furthermore, patients with high SEMA3F expressions did not only show fewer lymph node metastases but also less distant metastases in colorectal cancer." (PMID 39232098, 2024). "The aim of the present study is to analyze the predictive capacity of the transcriptional expression of SEMA3F and NRP2 in determining the presence of occult lymph node metastases in patients with HNSCC." (PMID 35565388, 2022).
prostate carcinoma (3 papers, 2019 to 2025). A carcinoma that arises from epithelial cells of the prostate gland. "Single nucleotide polymorphisms of sema3F are associated with increased prostate cancer risk and poor prognosis." (PMID 30696103, 2019). "Single nucleotide polymorphisms in the genes encoding sema3B and sema3F were also associated with prostate cancer risk and poor prognosis of prostate cancer." (PMID 30696103, 2019). "Simultaneously, as IGF2BPs co-target, SEMA3F was correlated with the survival of PCa patients, suggesting it might be a promising biomarker and predicting the risk of prostate cancer in the future." (PMID 38658974, 2024). "Overexpression of SEMA3F markedly enhanced docetaxel chemosensitivity in prostate cancer via regulating Hippo pathway." (PMID 38658974, 2024). "Altogether, our data showed that RBM15 and IGF2BPs play tumor suppressor roles via SEMA3F-mediated regulation of Hippo pathway in prostate cancer." (PMID 38658974, 2024). "As SEMA3F is correlated with prostate cancer patient survival, the precise regulation of R-loops by m6A and the resulting crosstalk between m6A and DNA methylation play important roles in prostate cancer." (PMID 40558832, 2025). "Additionally, overexpression of IGF2BPs in prostate cancer cells led to an increase in R-loops, suppressed cell migration, and reduced cell growth by upregulating SEMA3F—a gene with tumor suppressor functions in prostate cancer." (PMID 40558832, 2025). "Consequently, IGF2BPs overexpression leads to increased overall R-loop levels, cell migration inhibition, and cell growth retardation in prostate cancer (PCa) via precluding the binding of DNA methyltransferase 1(DNMT1) to semaphorin 3 F (SEMA3F) promoters." (PMID 38658974, 2024). "Further evaluation of the mechanism for the RBM15/IGF2BPs/SEMA3F axis may provide a new strategy for prostate cancer." (PMID 38658974, 2024).
cognitive decline (2 papers, 2018 to 2022). "This step identifies a specific set of largely neuronal genes, such as STAU1 and SEMA3F, predicted to control cognitive decline in older adults." (PMID 30140277, 2018).
depression (2 papers, 2016 to 2023). "However, given that the two types of test are used as a measurement of depression-related behavior, further studies are needed to clarify the role of Sema3F in the regulation of depression-related behavior." (PMID 26856818, 2016).
lymphoma (2 papers, 2014 to 2019). A malignant (clonal) proliferation of B- lymphocytes or T- lymphocytes which involves the lymph nodes, bone marrow and/or extranodal sites. "The expression levels and functional activities of SEMA3B, SEMA3F, and Neuropilin-2 have furthermore been investigated in leukemias and lymphoma cells." (PMID 31143707, 2019). "Moreover, NRP2 and SEMA3F are expressed in human T-cell acute lymphoblastic leukemia/lymphoma primary cells." (PMID 25068647, 2014). "SEMA3F is generally considered as a tumor suppressor gene and its expression is often downregulated in solid tumors, but its function could be different in leukemia and lymphomas, and awaits clarification." (PMID 31143707, 2019). "Based on our results regarding normal T cell precursors, we hypothesized that NRP2 and SEMA3F could also be expressed by malignant T cell precursors and have a role on lymphoblast migration which may explain various clinical patterns of disease presentation e.g. leukemic vs. lymphoma." (PMID 25068647, 2014). "Moreover, SEMA3F and its receptor Neuropilin-2/NRP2 were found to be highly expressed in human T-cell acute lymphoblastic leukemia/lymphoma primary cells, but SEMA3F was shown to inhibit the migration of malignant cells induced by CXCL12 and S1P." (PMID 31143707, 2019).
metastatic tumor (2 papers, 2018 to 2020). "Therefore, a balance of netrin-1 and SEMA3F in tumor cells might be a diagnostic and prognostic biomarker for a high metastatic tumor." (PMID 30532711, 2018). "Interestingly, even the genes that showed no differential expression in tumors compared to normal samples also showed significantly increased (NRP2 and PLXNC1) or decreased (PLXNB1 and SEMA3F) expression in metastatic tumors (p < 0.0001)." (PMID 32640719, 2020).
osteosarcoma (2 papers, 2020 to 2025). A usually aggressive malignant bone-forming mesenchymal neoplasm, predominantly affecting adolescents and young adults. "Knockdown of SEMA3F leads to an increased migration and metastasis of osteosarcoma SaOS and MG-63 cells and spleen-xenografted HCT116 colon cancer cells." (PMID 41391772, 2025).
preeclampsia (2 papers, 2017 to 2024). Preeclampsia is a hypertensive disorder of pregnancy that is characterized by new-onset hypertension with proteinuria presenting after 20 weeks of gestation, and depending on mild or severe forms may initially present with severe headache, visual disturbances, and hyperreflexia. "On this basis, we investigated whether semaphorin 3F might be involved in the development of late onset preeclampsia." (PMID 28350837, 2017). "We hypothesized that placenta ischemia, featuring preeclampsia, might induce the down-regulation of the anti-angiogenic system represented by semaphorin 3F and its receptor, NRP-2, in the attempt to improve placenta angiogenesis and blood supply." (PMID 28350837, 2017). "Semaphorin 3F was constitutively expressed by the endothelial cells of chorionic villi in normal placenta, while its placenta expression was markedly reduced in patients with preeclampsia." (PMID 28350837, 2017). "We aimed to investigate whether semaphorin 3F expression is modulated in preeclampsia." (PMID 28350837, 2017). "In addition, our findings support the hypothesis that amniotic fluid levels of semaphorin 3F might represent a predictive biomarker of preeclampsia." (PMID 28350837, 2017). "Semaphorin 3F might represent a predictive biomarker of preeclampsia." (PMID 28350837, 2017). "In addition, a decreased semaphorin 3F concentration in the amniotic fluid was already present at 16–18 weeks of gestation, potentially suggesting this anti-angiogenic factor as a predictive biomarker of preeclampsia." (PMID 28350837, 2017). "In addition, this observation might also suggest a role for semaphorin 3F as an early predictive biomarker of preeclampsia." (PMID 28350837, 2017). "In this regard, high SEMA3C levels have been found at the maternal–fetal–placental interface during the first trimester of gestation, and SEMA3F, SEMA3B, and NRP2 are overexpressed in the placenta of women with preeclampsia." (PMID 38541683, 2024). "Noteworthy, serum semaphorin 3F levels in patients with preeclampsia were comparable to those of non-pregnant health female controls (n = 40) (2.01±0.33 vs. 1.70±0.30 ng/mL, p = 0.07)." (PMID 28350837, 2017).
status epilepticus (2 papers, 2019 to 2021). Status epilepticus is defined as a continuous seizure lasting more than 30 min, or two or more seizures without full recovery of consciousness between any of them. "Similarly, the expression of Sema3F protein in the dentate gyrus is decreased in a lithium-pilocarpine-induced status epilepticus mouse model, in parallel to mossy fiber sprouting occurring in that region, suggesting that reduced expression of Sema3F may facilitate anomalous growth of mossy fibers." (PMID 34045951, 2021). "Because secretion of Sema3F by CA1 pyramidal cells may constrain axonal sprouting, reduced levels of Sema3F after induced status epilepticus may favor axonal remodeling and synapse reorganization, which are likely to provoke seizures." (PMID 34045951, 2021).
acute kidney injury (1 paper, 2024). Sudden and sustained deterioration of the kidney function characterized by decreased glomerular filtration rate, increased serum creatinine or oliguria. "Furthermore, the kinetics of SEMA were related to sepsis complications; SEMA3A, SEMA3C, SEMA3F, and SEMA4D were related to respiratory failure; SEMA3C and SEMA7A were related to acute kidney injury, while SEMA3C and SEMA3F were related to septic shock." (PMID 39770766, 2024).
alcohol (1 paper, 2023). "We observe positive colocalization [posterior probability (PP) > 80%] for 5 of 18 proteins with the same traits (ADGRE2 and total cholesterol [TC]; ANGPTL7 and BMI, waist-hip ratio; ITGB7 and TC; NOMO1 and LDL, TC; SEMA3F and BMI, alcohol use), supporting the two-sample MR results." (PMID 37550624, 2023).
autism spectrum disorder (1 paper, 2019). A spectrum of developmental disorders that includes autism, and Asperger syndrome. "Genome-wide association and other genetic studies have implicated at least 500+ genes associated with the occurrence of autism spectrum disorders (ASD) including the human semaphorin 3F (Sema 3F) and neuropilin 2 (NRP2) genes." (PMID 30635860, 2019).
cardiac arrest (1 paper, 2023). Cessation of breathing and/or cardiac function. "By modulating SEMA3F, RTX could potentially reduce the risk of HF, prolong survival, prevent fatal arrhythmias that cause cardiac arrest and most certainly reduce the inflammation after MI." (PMID 37588971, 2023).
chronic obstructive pulmonary disease (1 paper, 2020). A chronic and progressive lung disorder characterized by the loss of elasticity of the bronchial tree and the air sacs, destruction of the air sacs wall, thickening of the bronchial wall, and mucous accumulation in the bronchial tree. "We first explored SEMA3F expression in chronic obstructive pulmonary disease (COPD), a disease characterized by neutrophilic inflammation." (PMID 32191647, 2020).
COVID-19 (1 paper, 2023). A disease caused by infection with severe acute respiratory syndrome coronavirus 2. "Furthermore, we showed an association of semaphorin levels with COVID-19 severity; SEMA3F and SEMA7A were higher in critical COVID-19, while SEMA3A and SEMA3C negatively correlated with COVID-19 severity and were lower in the critical group." (PMID 37893159, 2023). "Concentrations of the serum semaphorins SEMA3A, SEMA3C, SEMA3F, SEMA4D and SEMA7A were detectable in all patients with COVID-19." (PMID 37893159, 2023). "In contrast, serum concentrations of SEMA3F and SEMA7A positively correlated with COVID-19 severity, with the highest levels in patients with critical COVID-19." (PMID 37893159, 2023). "In conclusion, we have shown that patients with COVID-19 have different expressions of SEMA3A, SEMA3C, SEMA3F and SEMA7A than healthy controls, which correlate with disease severity and outcomes." (PMID 37893159, 2023). "In conclusion, we provide the first evidence that SEMA3A, SEMA3C, SEMA3F and SEMA7A can be considered as new biomarkers of COVID-19 severity." (PMID 37893159, 2023). "While SEMA3A was decreased, SEMA3C, SEMA3F and SEMA7A were increased in COVID-19." (PMID 37893159, 2023). "To summarize, the SEMA3F and SEMA7A in COVID-19 might regulate vascular permeability and cytoskeletal remodeling along with neutrophil migration and retention in inflamed tissue, which leads to the amplification of inflammation." (PMID 37893159, 2023).